SMARCA1 (SNF2 related chromatin remodeling ATPase 1)
Description:
[Isoform 1]: ATPase that possesses intrinsic ATP-dependent chromatin-remodeling activity. ATPase activity is substrate-dependent, and is increased when nucleosomes are the substrate, but is also catalytically active when DNA alone is the substrate. Catalytic subunit of ISWI chromatin-remodeling complexes, which form ordered nucleosome arrays on chromatin and facilitate access to DNA during DNA-templated processes such as DNA replication, transcription, and repair. Within the ISWI chromatin-remodeling complexes, slides edge- and center-positioned histone octamers away from their original location on the DNA template. Catalytic activity and histone octamer sliding propensity is regulated and determined by components of the ISWI chromatin-remodeling complexes. The BAZ1A-, BAZ1B-, BAZ2A- and BAZ2B-containing ISWI chromatin-remodeling complexes regulate the spacing of nucleosomes along the chromatin and have the ability to slide mononucleosomes to the center of a DNA template. The CECR2- and RSF1-containing ISWI chromatin-remodeling complexes do not have the ability to slide mononucleosomes to the center of a DNA template. Within the NURF-1 and CERF-1 ISWI chromatin remodeling complexes, nucleosomes are the preferred substrate for its ATPase activity. Within the NURF-1 ISWI chromatin-remodeling complex, binds to the promoters of En1 and En2 to positively regulate their expression and promote brain development. May promote neurite outgrowth. May be involved in the development of luteal cells. Facilitates nucleosome assembly during DNA replication, ensuring replication fork progression and genomic stability by preventing replication stress and nascent DNA gaps. [Isoform 2]: Catalytically inactive when either DNA or nucleosomes are the substrate and does not possess chromatin-remodeling activity. Acts as a negative regulator of chromatin remodelers by generating inactive complexes.
Synonyms: SNF2L; SNF2L1; SNF2LB; NURF140; ISWI; SWI; hSNF2L; SNF2LT; SWI2
Tractability: PROTAC: UniProt records ubiquitination sites on it; ubiquitination databases record sites on it; its protein half-life has been measured.
Target class: Enzyme; Hydrolase
Gene: Protein-coding gene on chromosome X (129,446,501 to 129,523,947, reverse strand). Ensembl gene ENSG00000102038.
Subcellular location: Nucleus; Chromosome
Subcellular location (Human Protein Atlas): Nucleoplasm; Vesicles
Gene Ontology:
Molecular function: ATP hydrolysis activity; ATP-dependent activity, acting on DNA; ATP-dependent chromatin remodeler activity; ATP-dependent DNA/DNA annealing activity; protein binding; RNA polymerase II-specific DNA-binding transcription factor binding; helicase activity; ATP binding; DNA binding; nucleosome binding
Biological process: brain development; chromatin remodeling; positive regulation of DNA-templated transcription; positive regulation of transcription by RNA polymerase II; regulation of DNA-templated transcription; neuron differentiation
Cellular component: ATPase complex; CERF complex; chromosome; nucleoplasm; nucleus; NURF complex
Gene-disease validity (ClinGen):
ClinGen rates the evidence that SMARCA1 causes each of these diseases.
X-linked intellectual disability (X-linked): Limited. An X-linked intellectual deficiency in which not enough information is known, reported or published to indicate whether a gene causes non-syndromic or syndromic presentations.
Homologues: Orthologues: macaque SMARCA1 (100% identical), chimpanzee SMARCA1 (99% identical), pig SMARCA1 (97% identical), rabbit SMARCA1 (97% identical), mouse Smarca1 (95% identical), guinea pig SMARCA1 (95% identical), rat Smarca1 (93% identical), tropical clawed frog smarca1 (85% identical), zebrafish smarca1 (81% identical), Drosophila melanogaster Iswi (69% identical), Caenorhabditis elegans isw-1 (59% identical). Paralogues in human: SMARCA5 (80% identical), CHD2 (33% identical), CHD1 (31% identical), INO80 (29% identical), SMARCA4 (28% identical), HELLS (27% identical), SRCAP (27% identical), CHD7 (27% identical), SMARCA2 (27% identical), CHD5 (27% identical), CHD3 (26% identical), CHD4 (26% identical), and 18 more.
Diseases named in the same sentence as SMARCA1 in open-access papers:
SMARCA1 is named in the same sentence as 79 diseases in open-access papers, as found by Europe PMC text mining. Sharing a sentence is not in itself a finding about the gene and the disease. The quoted sentences say what the papers report.
colorectal cancer (9 papers, 2017 to 2024). A primary or metastatic malignant neoplasm that affects the colon or rectum. "DLEU1 recruits SMARCA1 to epigenetically activate the KPNA3 gene in colorectal cancer, thereby promoting cell proliferation and migration." (PMID 35619131, 2022). "In terms of mechanism, we found that DLEU1 co-localized with SMARCA1 in colorectal cancer cells." (PMID 30098595, 2018). "For instance, DLEU1 is upregulated in colorectal cancer (CRC) and recruits SMARCA1 to epigenetically activate a downstream target gene, KPNA3, which leads to CRC progression." (PMID 34650128, 2021). "LncRNA DLEU1 recruits SMARCA1 to the KPNA3 promoter and activates its transcription, thereby promoting the proliferation and migration of colorectal cancer." (PMID 32661324, 2020). "Collectively, DLEU1 recruited SMARCA1 to epigenetically activate downstream gene KPNA3, thereby promoting proliferation and migration in colorectal cancer." (PMID 30098595, 2018). "In colorectal cancer tissues, by activating KPNA3 via recruiting SMARCA1, an essential subunit of the NURF chromatin remodelling complex, increased expression of DLEU1 was observed, and higher expression of DLEU1 in patients indicated lower survival rate and a poorer prognosis." (PMID 32742772, 2020). "However, SMARCA1 was absent in the colon, according to protein expression data from the Human Protein Atlas (accessed 6/28/2024), underscoring the specific partnership between BAZ1A and SMARCA5 in colorectal cancer." (PMID 39112459, 2024).
breast carcinoma (7 papers, 2017 to 2025). "For breast cancer, low SMARCA1 expression was linked to poor OS (P = 0.04), relapse-free survival (RFS) (P = 0.011) and distant metastasis-free survival (DMFS) (P = 0.019) but not progress-free survival (PFS)." (PMID 36126083, 2022). "Another member of the ISWI subfamily implicated in breast cancer progression is the Remodeling and Spacing Factor (RSF) complex, which consists of a chaperone nuclear protein and SMARCA5 or SMARCA1." (PMID 41278204, 2025). "Exon inclusion in SPPL2A and exon exclusion in SMARCA1 were observed not only in LADC, but also in MDA-MB-231 cells, a breast cancer cell line with a truncating CMTR2 mutation." (PMID 41198678, 2025). "We performed a meta-analysis to validate the correlation observed in breast cancer (P = 0.001), lung cancer, ovarian cancer and gastric cancer (all P < 0.001) again and to identify any potential SMARCA1-prognosis correlation in liver cancer (P = 0.021)." (PMID 36126083, 2022). "Subgroup analysis on the correlation of SMARCA1 expression and prognosis of breast cancer cases." (PMID 36126083, 2022). "According to the analysis using the CPTAC database, we found that SMARCA1 total protein expression was higher in the primary tumor tissues of breast cancer, clear cell RCC, LUAD (P < 0.001), and ovarian cancer (P < 0.05) than in normal tissues except in the case of UCEC." (PMID 36126083, 2022). "Our study discovered that a low expression of SMARCA1 was correlated with poor OS, RFS and DMFS in breast cancer based on large sample sizes." (PMID 36126083, 2022). "SMARCA1 plays a vital role in maintaining cell survival and cell cycle progression, as inhibition of SMARCA1 leads to the upregulation of Apoptotic Protease Activating Factor 1 (APAF1) and thus increased activity of caspase 9 in primary breast cancers." (PMID 41278204, 2025). "Hence, a further study confirming their expression levels and functions in various subtypes of breast cancer is needed, as the balanced expression of SMARCA5 and SMARCA1 may be of interest for therapeutic purposes." (PMID 41278204, 2025). "Down-regulated SMARCA1 might contribute to DNA injury, growth restriction and tumor cell apoptosis in breast cancer were previously reported, without providing prognosis analysis and other bioinformation." (PMID 36126083, 2022).
gastric cancer (5 papers, 2016 to 2022). A primary or metastatic malignant neoplasm involving the stomach. "For gastrointestinal tumors, up-regulated SMARCA1 expression was considered to be correlated with colorectal and gastric cancer through different pathways." (PMID 36126083, 2022). "A recent study on gastric carcinomas found SMARCA1 silenced by aberrant methylation in gastric cancer cells." (PMID 31093468, 2018). "During gastric carcinogenesis, aberrant methylation of an ISWI component, SMARCA1, was detected in normal gastric tissues of people infected with Helicobacter pylori, a potent gastric cancer inducer." (PMID 26812616, 2016). "Subgroup analysis on the correlation of SMARCA1 expression and prognosis of gastric cancer cases." (PMID 36126083, 2022). "In contrast, high SMARCA1 expression was related to poor OS (P = 0.037), PFS (P < 0.001) and PPS (P = 0.047) in ovarian cancer, as well as to OS (P < 0.001), FP (P < 0.001) in gastric cancer." (PMID 36126083, 2022). "Besides its correlation with non-neoplastic diseases, SMARCA1 has also been observed in numerous malignancies, such as soft tissue sarcoma, colorectal cancer, gastric cancer, and urothelial cancer." (PMID 36126083, 2022).
liver cancer (5 papers, 2020 to 2025). An epithelial or non-epithelial malignant neoplasm that arises from the liver. "Although it could be affected by heterogeneity, model, effect size, sample size, bias, etc., the meta-analysis indicated a potentially high risk of poor prognosis in liver cancer with elevated SMARCA1 expression to (P = 0.021)." (PMID 36126083, 2022). "Subgroup analysis on the correlation of SMARCA1 expression and prognosis of liver cancer cases." (PMID 36126083, 2022). "SMARCA1 expression has been found to be correlated with liver cancer in a few studies." (PMID 36126083, 2022).
ovarian carcinoma (4 papers, 2019 to 2025). A malignant neoplasm originating from the surface ovarian epithelium. "A similar phenomenon was observed in ovarian cancer: transcriptional SMARCA1 expression was low in tumor tissues accompanied by a high protein expression, with the increased expression correlating with poor OS, PFS, and PPS of OV." (PMID 36126083, 2022). "Subgroup analysis on the correlation of SMARCA1 expression and prognosis of ovarian cancer cases." (PMID 36126083, 2022).
Intellectual disability (3 papers, 2008 to 2023). "Among those genes, SMARCA1 has been associated with syndromic intellectual disability and Coffin-Siris-like features by the Clinical Genome Resource (ClinGen) with moderate evidence." (PMID 36323681, 2022).
lung carcinoma (3 papers, 2021 to 2024). "Restoration of SMARCA1 in vivo significantly reduced lung cancer invasiveness and c-MYC expression, suggesting that inactivated SMARCA1 keeps cancer cells in an undifferentiated state and prevents its response to developmental and environmental stimuli." (PMID 33968920, 2021). "The inconsistent in LUAD might due to the sample size and as a result, the opposite role of SMARCA1 in patient prognosis with different lung cancer histopathology needs further investigation with more extensive sample size studies." (PMID 36126083, 2022). "Subgroup analysis on the correlation of SMARCA1 expression and prognosis of lung cancer cases." (PMID 36126083, 2022).
melanoma (3 papers, 2015 to 2021). A malignant, usually aggressive tumor composed of atypical, neoplastic melanocytes. "Forced expression of SMARCA1 in melanoma cells inhibits cell proliferation and metastasis by attenuating Wnt/β-catenin signaling." (PMID 34736517, 2021). "We next interrogated transcriptome data to assess expression of the BPTF, SMARCA1 and SMARCA5 subunits of NURF in a collection of human melanoma cells." (PMID 26440048, 2015). "Similarly, SMARCA1 is strongly expressed in normal melanocytes but is widely absent in malignant melanoma." (PMID 34736517, 2021).
neuroblastoma (3 papers, 2019 to 2021). Neuroblastoma (NB) is the most common solid, extracranial childhood tumor. "Here, we show that elevated SMARCA4 expression corresponds strongly to poor outcomes for neuroblastoma patients, whereas elevated expression of SMARCA1 correlates to good outcome, suggesting antagonist roles in neuroblastoma for members of this gene family." (PMID 33968920, 2021). "Conversely, in SH-SY5Y neuroblastoma cells, a commonly used model system of retinoid-dependent differentiation, attenuated expression of SMARCA1 prevented response to retinoids." (PMID 33968920, 2021).
schizophrenia (3 papers, 2022 to 2025). A major psychotic disorder characterized by abnormalities in the perception or expression of reality. "One other individual carrying the p.Ile647Thr variant also developed psychotic symptoms suggesting that SMARCA1 is involved in the biological pathways implicated in schizophrenia." (PMID 37841849, 2023). "SMARCA1 was previously reported to play a vital role in the maturation of midbrain dopaminergic (mDA) neurons and is related with multiple mechanisms in neurogenesis or schizophrenia." (PMID 36126083, 2022). "For example, TFs SMARCA1, TCF4, and TRPS1 have been confirmed to play crucial roles in schizophrenia, and they have been confirmed to target CRABP1." (PMID 39905509, 2025).
CNS cancer (2 papers, 2022). "This study attempted to use several tools to assess the correlation between SMARCA1 expression and CNS malignant tumors." (PMID 36126083, 2022). "Additionally, the correlation between SMARCA1 and brain and CNS cancer was verified again via the Oncomine database (P = 7.64e-06)." (PMID 36126083, 2022). "Furthermore, SMARCA1 expression in the cytoplasm and nucleus reaches moderate intensity in glioma, prostate and renal." (PMID 36126083, 2022).
colon adenocarcinoma (2 papers, 2021 to 2022). "The expression level of SMARCA1 was positively correlated with cancer-associated fibroblasts infiltration in a number of tumors, such as colon adenocarcinoma, cervical squamous cell carcinoma and endocervical adenocarcinoma." (PMID 36126083, 2022). "Through analysis of TCGA database, the SMARCA5 and SMARCA1 gene have divergent patterns of expression in cancers, such as colon adenocarcinoma (COAD), LUAD and stomach adenocarcinoma (STAD), suggesting that they have differential roles or even opposing roles." (PMID 34736517, 2021).
hepatocellular carcinoma (2 papers, 2021 to 2025). A malignant tumor that arises from hepatocytes. "Correspondingly, high expression of the SMARCA1-NURF complex, ZIC2 and OCT4 are positively correlated with the clinicopathological stages of hepatocellular carcinoma (HCC)." (PMID 34736517, 2021).
Lowe syndrome (2 papers, 2019 to 2022). "Similarly, in our study, the patient harboring the interstitial deletion encompassing OCRL and SMARCA1 gene presented with severe features of Lowe syndrome after birth and died at 7 months of age from unknown causes." (PMID 31376231, 2019). "Therefore, it could not be excluded the possibility that additional features caused by the deletion of SMARCA1 aggravate the phenotype of Lowe syndrome." (PMID 31376231, 2019). "This is the first report of an interstitial deletion encompassing OCRL and SMARCA1 gene in Lowe syndrome." (PMID 31376231, 2019). "Here, we identified an interstitial deletion encompassing the OCRL and SMARCA1 gene in an affected male with severe features of Lowe syndrome." (PMID 31376231, 2019). "We identified four variants of the OCRL gene in four patients with Lowe syndrome, including two novel missense mutations, one recurrent nonsense mutation and a microdeletion encompassing OCRL and SMARCA1 gene." (PMID 31376231, 2019).
lung adenocarcinoma (2 papers, 2022 to 2024). A carcinoma that arises from the lung and is characterized by the presence of malignant glandular epithelial cells. "Increasingly, novel genes such as SMARCA1, SMARCA4 and SMAD4 alterations in lung adenocarcinoma are independently associated with LNM in lung adenocarcinoma." (PMID 39720561, 2024). "Furthermore, we analyzed lung adenocarcinoma (n = 865) and squamous cell carcinoma (n = 675) cases from all cohorts, revealing that low SMARCA1 expression was correlated with poor OS, FP and PPS in LUAD, however high expression was associated with poor FP in LUSC." (PMID 36126083, 2022).
pancreatic cancer (2 papers, 2021). "On the one hand, high SMARCA1 mRNA expression was observed in pancreatic cancer, and SMARCA1 mRNA expression was remarkably correlated with tumor stages." (PMID 34315468, 2021). "On the other hand, high mRNA SMARCA1 expression was significantly correlated with favorable OS in patients with pancreatic cancer." (PMID 34315468, 2021). "The role of chromatin remodeling in pancreatic cancer has been heavily investigated as several genes involved in histone methylation (MLL2 and MLL3) and members of the tumor suppressing SWI/SNF complex (SMARCA1 and ARID1A) are recurrently mutated in PDAC tumors." (PMID 34049503, 2021). "Little was known about the physiological functions of SMARCA1 in pancreatic cancer." (PMID 34315468, 2021). "Therefore, further studies consist of larger sample sizes worth to validate SMARCA1 expression patterns in patients with pancreatic cancer and to explore the roles of SMARCA1 in tumorigenesis." (PMID 34315468, 2021).
sarcoma (2 papers, 2018 to 2023). A usually aggressive malignant neoplasm of the soft tissue or bone. "SMARCA1 IHC was studied in the sarcoma subtypes with potential SMARCA1 alterations in our institutional cases." (PMID 31093468, 2018). "SMARCA1 nuclear expression was lost in 3 of 10 cases (30%) of undifferentiated sarcomas." (PMID 31093468, 2018). "None of the other sarcoma subtypes had SMARCA1 genomic alterations." (PMID 31093468, 2018).
Arthritis (1 paper, 2024). Inflammation of a joint. "Future studies will reveal a specific role for SMARCA1 in shaping gene expression in arthritis." (PMID 39235454, 2024).
cholangiocarcinoma (1 paper, 2022). A carcinoma that arises from the intrahepatic biliary tree (intrahepatic cholangiocarcinoma) or from the junction, or adjacent to the junction, of the right and left hepatic ducts (hilar cholangiocarcinoma). "Based on TIMER2 analysis, SMARCA1 expression was high in tumor tissues of LIHC but low in cholangiocarcinoma (CHOL)." (PMID 36126083, 2022).
Coffin-Siris syndrome (1 paper, 2021). Coffin-Siris syndrome (CSS) is a rare congenital multi-systemic genetic disorder characterized by aplasia or hypoplasia of the distal phalanx or nail of the fifth digit, developmental delay, intellectual disability, coarse facial features, and other variable clinical manifestations. "The same corresponding mutations occurring in SMARCA1, SMARCA4, and SMARCA2 (components of a closely related chromatin remodeling complex known as SWI//SNF) cause Schimke immune-osseous dysplasia, Coffin–Siris syndrome and Nicolaides–Baraitser syndrome." (PMID 33981601, 2021).
gastric tumor (1 paper, 2021). "SMARCA1 knockdown promotes the growth of gastric tumor cells, accompanied by downregulation of genes related to cellular homeostasis." (PMID 34736517, 2021). "For example, in gastric tumor cells, the circ-DONSON recruits the SMARCA1-NURF complex to the SOX4 promoter by directly interacting with SMARCA1, which facilitates tumor cell development via enrichment of the active markers H3K27ac and H3K4me3 on the promoter and activation of SOX4 transcription." (PMID 34736517, 2021).